MIR6128 (microRNA 6128)
Synonyms: hsa-mir-6128
Gene: MicroRNA gene on chromosome 11 (56,743,873 to 56,743,981, forward strand). Ensembl gene ENSG00000274770.
Homologues: Orthologues: chimpanzee ptr-mir-6128 (100% identical).